PRNP (prion protein (Kanno blood group))
Diseases named in the same sentence as PRNP in open-access papers (continued):
Sharing a sentence is not in itself a finding about the gene and the disease.
sporadic CJD (39 papers, 2009 to 2025). "Except for one group, Martins 2007, the genotype frequencies of M129V of the PRNP gene exhibited a strong association (p < 0.05) with susceptibility to sporadic CJD in all groups tested." (PMID 34831353, 2021). "In previous genome-wide association studies (GWAS), the locus of the PRNP gene was found to be extremely related to susceptibility to sporadic CJD." (PMID 34831353, 2021). "Previous studies have shown that codon 129 polymorphism of the human PRNP gene in the Asian population has rarely been found in sporadic CJD patients, and the heterozygote of this SNP has been considered to have a resistant effect." (PMID 34831353, 2021). "We performed a meta-analysis on qualifying studies and identified a significant association between the M129V SNP of the PRNP gene and susceptibility to sporadic CJD in all genetic models, except for the homozygote comparison." (PMID 34831353, 2021). "Several case–control studies using fine mapping have also identified that the nonsynonymous polymorphism at codon 129 of the PRNP gene is significantly associated with susceptibility to sporadic CJD." (PMID 34831353, 2021). "In the present study, we evaluated the association between the M129V SNP of the PRNP gene and susceptibility to sporadic CJD using a meta-analysis." (PMID 34831353, 2021). "In human prion diseases, the M129V SNP of the human PRNP gene plays a pivotal role in susceptibility to sporadic CJD." (PMID 35097050, 2021). "We performed a meta-analysis by collecting data from eligible studies to evaluate the association between the M129V SNP of the PRNP gene and susceptibility to sporadic CJD." (PMID 34831353, 2021). "Then, we performed a meta-analysis by collecting data from eligible studies to evaluate the association of the M129V SNP of the PRNP gene with susceptibility to sporadic CJD." (PMID 34831353, 2021). "In conclusion, we identified a strong association between the M129V SNP of the PRNP gene and susceptibility to sporadic CJD using a meta-analysis for the first time." (PMID 34831353, 2021). "We found a very strong association between the M129V SNP of the PRNP gene and susceptibility to sporadic CJD using a meta-analysis for the first time." (PMID 34831353, 2021). "To evaluate the association between the M129V SNP of the PRNP gene and susceptibility to sporadic CJD, we collected data on the genotype and allele frequencies of the M129V SNP of the PRNP gene and information on ethnic backgrounds from sporadic CJD patients." (PMID 34831353, 2021). "We collected data that contain the genotype and allele frequencies of the M129V single-nucleotide polymorphism (SNP) of the PRNP gene and information on ethnic backgrounds from sporadic CJD patients." (PMID 34831353, 2021). "The conformational change of PrPC can occur due to either one of three causes: spontaneous conversion in sporadic CJD (sCJD), mutations in the PRNP gene in genetic CJD, or infection with PrPSc in iatrogenic CJD and variant CJD." (PMID 24685293, 2014). "The PRNP polymorphism at codon 219 is unique to Asian populations, and PRNP 219EK heterozygous genotype has a protective effect on sporadic CJD development." (PMID 21838916, 2011). "While the etiology of sporadic CJD remains unknown, it is hypothesized that a somatic mutation in the prion protein (PRNP) or misfolding of PrPc into PrPsc might underlie the etiopathogenesis of CJD." (PMID 36768596, 2023). "Thus, a comprehensive evaluation of the association between polymorphisms of the PRNP gene at codon 129 and susceptibility to sporadic CJD is needed in quality-checked and quantitatively synthesized studies." (PMID 34831353, 2021). "Although the overrepresented M129 allele of the PRNP gene was observed in Asian populations (>90%), including Korea and Japan, the incidence of sporadic CJD is similar and/or low compared to European populations, which have a relatively low frequency of the M129 allele (<70%)." (PMID 35097050, 2021).
sporadic CJD (continued). "To identify an association between the M129V SNP of the PRNP gene and susceptibility to sporadic CJD, we performed an association analysis between sporadic CJD patients and matched control populations, including Caucasian and East Asian populations obtained from the 1000 Genomes Project." (PMID 34831353, 2021). "In order to identify whether the RPSA polymorphism affects susceptibility to sporadic CJD, we tested for LD with PRNP codon 129 polymorphism." (PMID 21838916, 2011). "Polymorphisms at codons 129 or 219 of PRNP are susceptibility factors to sporadic CJD." (PMID 19351416, 2009). "Consequently, certain variables associated with survival, such as those reflecting deposition secondary to geographically different PRNP gene mutations, might constitute risk factors for different forms of sporadic CJD in Western and Asian/Japanese populations." (PMID 35126037, 2021). "The Glu219Lys is also a PRNP SNP well-known for its protective effects against sporadic CJD, and the equivalent substitution in mouse PrP (Gln218Lys) is also protective against mouse-adapted scrapie." (PMID 31340582, 2019). "In this work, we investigated for the first time, APOE and PRNP genotypes simultaneously in 474 AD and 175 sporadic CJD (sCJD) patients compared to a common control population of 335 subjects." (PMID 21799773, 2011). "In conclusion, although we found possibly pathogenic PRNP variants in 2 participants with sporadic CJD, overall, there was no increased burden of variants in brain tissue from participants with sCJD compared with controls." (PMID 36686280, 2023). "The most conservative interpretation of our findings is that somatic PRNP mutations are not enriched in sporadic CJD brains, but there are alternative explanations for our findings." (PMID 36686280, 2023). "Creutzfeldt-Jakob disease (CJD), the most frequent TSE, exists in three forms: sporadic CJD (sCJD), of unknown aetiology; genetic CJD (gCJD), i.e. caused by mutations in PrP-encoding gene, PRNP; and acquired CJD, either variant (vCJD) or accidentally transmitted (atCJD)." (PMID 34120571, 2021). "Thus far, more than 50 mutations in PRNP have been reported to cause autosomal dominant inherited CJD, and a large number of polymorphisms in PRNP (including codon 129, 219, 178, 200, and 232, etc.)have been identified as susceptible factors in sporadic CJD (sCJD) cases." (PMID 27910931, 2016). "In contrast, other inocula comprising sporadic CJD and iatrogenic CJD with different PRNP codon 129 status and PrPSc types, and also vCJD and vCJD passaged in 129VV Tg152 mice (which contained type 5 PrPSc) transmitted very poorly or not at all." (PMID 24086135, 2013). "Although PRNP 1368 polymorphism has been studied in sporadic CJD and FTLD patients, a case-controlled association study between the PRNP 1368 polymorphism and either AD or VaD has not been reported thus far." (PMID 19351416, 2009).
Cognitive impairment (31 papers, 2010 to 2025). Abnormal cognition is characterized by deficits in thinking, reasoning, or remembering. "We studied the association between the codon 129 polymorphism of the PRNP gene and mild cognitive impairment in 3605 participants from the Rotterdam Study using logistic regression analyses." (PMID 32954288, 2020). "In this study, we investigated the association of the M129V polymorphism of the PRNP gene with mild cognitive impairment and dementia." (PMID 32954288, 2020). "Previous studies have studied the effect of the M129V polymorphism of the PRNP gene in mild cognitive impairment and different types of dementia in Asians." (PMID 32954288, 2020). "In conclusion, we found a statistically significant higher prevalence of mild cognitive impairment in carriers of the methionine/methionine genotype in the codon 129 polymorphism of the PRNP gene within this population-based study." (PMID 32954288, 2020). "Not uncommonly in our gPrD families, we find that prior to a PRNP mutation being identified, some family members with gait ataxia and dementia were assumed to have had alcoholism causing cognitive impairment and gait problems." (PMID 24330864, 2013). "Our study showed that the M129V polymorphism of the PRNP gene may increase the prevalence of mild cognitive impairment." (PMID 32954288, 2020). "Similarities were seen between CBS patients with PRNP and MAPT mutations, with high recurrence in extrapyramidal symptoms, dystonia, oculomotor and bulbar dysfunction, cognitive impairment, and alien-limb phenomena." (PMID 33467748, 2021). "This could be a possible explanation for our finding that the M129V polymorphism of the PRNP gene plays a role in mild cognitive impairment, and not in dementia." (PMID 32954288, 2020).
breast carcinoma (30 papers, 2008 to 2025). "We then explored the underlying molecular pathway by which ER stress increased PRNP gene expression in the breast carcinoma MCF-7 cell line." (PMID 23497519, 2013). "Overall, these results suggest that ER stress is associated with increased PRNP gene expression in human breast cancer tumors with a basal subtype and poor outcome in human patients." (PMID 23497519, 2013). "Interestingly, ER stress-response elements have been found within the human PRNP promoter and they appear active, since PrPC expression was induced following treatment of breast carcinoma cells with toxins that cause ER stress." (PMID 28428956, 2017). "Other data indicate that PRNP may be implicated in the biology of glioblastoma, breast cancer, prostate and gastric cancer or, in other words, PRNP is involved in long term proliferation as are stem cells." (PMID 21483752, 2011). "Next, information from TCGA-BRCA revealed that breast cancer had considerably lower PRNP expression." (PMID 37535656, 2023). "In GSE21422 and GSE31192 datasets, we compared the expression of PRNP in breast cancer tissues to that in healthy tissues and found that the expression of PRNP was lower in BRCA tissues." (PMID 37535656, 2023). "Prion protein (PRNP) is involved in tumors, including glioblastoma, breast cancer, prostate cancer, gastric cancer, and CRC33." (PMID 34083586, 2021). "For instance, PRNP gene expression and PrPC protein levels were found to be upregulated in adriamycin-resistant MCF7 breast cancer cells, as well as in SNU-5C colorectal cancer cells resistant to 5-fluorouracil (5-FU) or oxaliplatin." (PMID 34638517, 2021). "Endoplasmic reticulum stress was a positive regulator of PRNP gene transcription breast cancer cell lines." (PMID 24287918, 2013). "Together, these results show that ER stress of the luminal breast carcinoma MCF-7 cell line increases PRNP gene transcription." (PMID 23497519, 2013). "Together, these results show that intrinsic or exogenous ER stress up-regulates PRNP gene expression in basal breast carcinoma cell lines." (PMID 23497519, 2013). "Our first observation in this study was that PRNP gene expression is regulated by ER stress in both basal and luminal breast cancer cell lines." (PMID 23497519, 2013). "Given that ER stress-mediated activation of the UPR occurs in cancer tissues and cell lines, we investigated its effect on PRNP gene expression in breast cancer." (PMID 23497519, 2013). "Previous studies have confirmed a link between PRNP(PrPC) and the occurrence and development of gastric cancer, CRC, lung cancer, and breast cancer, with its expression being linked to drug resistance, proliferation, apoptosis, migration, and invasion of various malignant tumor cells." (PMID 39170916, 2024). "Our research has constructed the most comprehensive breast cancer miRNA-gene interaction network through the integrated analysis of multiple breast cancer databases, and verified the interaction of miR-454 and PRNP and the function of PRNP in breast cancer proliferation." (PMID 33204705, 2020). "Related research shows that PRNP is an endoplasmic reticulum stress-regulated gene that could increase survival in breast cancers." (PMID 33204705, 2020). "Preliminary evidence suggests that endoplasmic reticulum (ER) stress may also regulate PRNP gene expression in breast cancer cells." (PMID 23497519, 2013). "We identified the expression of cuproptosis-related mRNA across five distinct breast cancer subtypes, revealing that only two genes, PDHB and PRNP, exhibited significant differential expression within this cohort." (PMID 38408075, 2024). "Also, 7 genes (CTGF, ESR1, MAPK3, PIK3R3, PLAU, PRNP, and RET) were reported to be highly relevant to growth (P<1E-04) and microtubule dynamics (P<4E-05) in tumor cell lines, and apoptosis in breast cancers (P<1E-04)." (PMID 23185353, 2012).
colorectal cancer (29 papers, 2014 to 2025). A primary or metastatic malignant neoplasm that affects the colon or rectum. "The expression of PRNP is positively associated with tumor development, drug resistance and poor prognosis in colorectal cancer, pancreatic carcinoma, breast cancer, hepatocellular carcinoma, esophageal squamous cell carcinoma, glioma and lung cancer." (PMID 38534516, 2024). "The prion protein encoded by the PRNP gene was reported to promote the cancer proliferation of gastric cancer, pancreatic ductal adenocarcinoma, colorectal cancer, glioblastoma, and schwannanoma 25-32." (PMID 35371305, 2022). "A first hint at a link between PrPC and immune-evasion can be inferred from the enrichment of PRNP gene expression in the mesenchymal subtype of colorectal cancer, itself associated with an immune-suppressive signature." (PMID 34638517, 2021). "Moreover, PRNP in tumors promoted the transformation of mesenchymal subtype and associated with poor survival through Hippo signaling pathway in colorectal cancer." (PMID 36213323, 2022). "Moreover, in colorectal cancer, we reported an enrichment in the expression of the PRNP gene in the mesenchymal subtype, itself associated with increased progression to advanced stages." (PMID 34638517, 2021). "Prior research demonstrated that hypoxia downregulation of hsa-miR-148a-3p led to the overexpression of its two target genes, ITGA5 and PRNP, which was a factor in colorectal cancer patients’ tumor development and poor prognosis." (PMID 36110217, 2022). "Similarly, PRNP silencing abrogates colorectal cancer cell stem-like and mesenchymal-like phenotype through inhibiting the recruitment of the Hippo pathway effectors YAP and TAZ, and the TGFβ pathway." (PMID 31618844, 2019). "Likewise, we documented that PrPC controls the expression of the EMT transcription factor ZEB1 in colorectal cancer cell lines and that PRNP gene expression is significantly correlated with an EMT signature in both colorectal cancer patients and cell panels." (PMID 34638517, 2021).
dementia (29 papers, 2011 to 2025). Loss of intellectual abilities interfering with an individual's social and occupational functions. "Taken together, their data suggested that miR-146a modulates PRNP, and its downregulation in db/db diabetic mice explains PrPC accumulation, previously known to be associated with the dementia-like phenotype." (PMID 34209482, 2021). "Future studies should further elucidate the role of the M129V polymorphism of the PRNP gene in cognitive function, dementia and other neurodegenerative traits." (PMID 32954288, 2020). "Unique phenotypes of dementia have been reported to carry S17G, P39L, Y163*, D167N, D187fs, and R208C mutations in the PRNP gene." (PMID 32560489, 2020). "Therefore, it is recommended to screen for PRNP mutations in patients with genetically undefined dementia or psychiatric symptoms." (PMID 36298800, 2022). "In addition, we found a similar alteration of allele frequencies compared the European population in sporadic patients and in V210I-CJD, a poorly penetrant PRNP mutation, and sAD, suggesting shared oligogenic patterns in different types of dementia." (PMID 35144616, 2022). "Reviewing the literatures indicates that the two cases in this report are the 2nd and 3rd dementia patients with S97N substitution in the PRNP gene." (PMID 37962387, 2023). "While the dementia seen in Creutzfeldt–Jakob disease patients is likely a result of prion protein aggregation, various studies suggest that the PRNP gene is also involved in other forms of dementia, but results are inconsistent." (PMID 32954288, 2020). "Furthermore, a compound heterozygous alteration of the TREM2 gene was identified in one patient and in two patients we found RDVs in other autosomal dominantly inherited genes also associated with dementia (CSF1R-ALSP, PRNP-CJD)." (PMID 35752680, 2022). "Specifically, because somatic mutations of the PRNP gene in glioblastoma, which occurs in the brain, can be masked by a diagnosis of dementia, the absence of somatic mutations in the PRNP gene in glioblastoma can be explained." (PMID 32560489, 2020). "No family members suffered from dementia, and the available DNA sequencing of her family members revealed no PRNP p.S17G mutation." (PMID 27910931, 2016). "In particular, PRNP, DNMT1 and APP play a role not only in the EOD but also in several other forms of dementia and brain diseases." (PMID 37819683, 2023). "First, we failed to perform screening of copy number variation (deletions or duplications) in the prion protein gene (PRNP), C9ORF72 (chromosome 9 open reading frame 72), and APP, which might be responsible for a proportion of EOAD and other types of dementia." (PMID 37051054, 2023).
Parkinson disease (27 papers, 2014 to 2026). A progressive degenerative disorder of the central nervous system characterized by loss of dopamine producing neurons in the substantia nigra and the presence of Lewy bodies in the substantia nigra and locus coeruleus. "Mutations in ATXN3, PRNP, and CACNA1A have been implicated in PD and parkinsonism through diverse mechanisms and clinical presentations in isolated cases." (PMID 41009775, 2025). "This case of Gerstmann-Sträussler-Scheinker disease, caused by the P102L mutation in the PRNP gene, is characterized by an atypical presentation of parkinsonism from the initial stages without ataxia, which is uncommon in most reported cases with this mutation." (PMID 41142443, 2025).
gastric cancer (26 papers, 2011 to 2025). A primary or metastatic malignant neoplasm involving the stomach. "Fan’s laboratory first found thd PRNP gene (encoding PrPc) was up-regulated in gastric cancer in 2002 and subsequently found that PrPc expression can enhance gastric cancer cell proliferation, migration and drug resistance." (PMID 38534516, 2024). "Resistance to apoptosis was the first hallmark to be connected with PrPC nearly 20 years ago, as PRNP transcripts were found to be upregulated in adriamycin-resistant SGC7901 gastric cancer cells as compared to the parental cell line." (PMID 34638517, 2021). "PRNP is associated with the prognosis of many cancers, such as gastric cancer, CRC and pancreatic cancer." (PMID 34170849, 2021).